BST2 (bone marrow stromal cell antigen 2)
Diseases named in the same sentence as BST2 in open-access papers (continued):
Sharing a sentence is not in itself a finding about the gene and the disease.
cancer (continued). "Similarly, hypermethylation of SHISA3, KCNA3, NPY, and hypomethylation of NUMB, BST2, MAPK13 promoters, which have previously been implicated in other cancers, robustly separate normal and GBC-OSCC samples." (PMID 37245006, 2023). "Dysregulation of BST2 expression has also been studied in several human cancers." (PMID 36594082, 2023). "BST2 function has been previously investigated in a variety of human cancers." (PMID 35865015, 2022). "It has been reported that BST2 is aberrantly expressed in cancers." (PMID 34692852, 2021). "An overview of different strategies adopted to suppress these IRDS genes (for example; STAT1, IRF7, OAS family and BST2) in cancer inducing the sensitivity (chemo- and radiotherapy), as well as different ways by which the viruses inhibit the IRDS genes are addressed in this review." (PMID 33922087, 2021). "We have previously shown that B49Mod1 is a BST-2-based peptide that inhibits cancer cell adhesion." (PMID 32155736, 2020). "The identification of a shorter bioactive fragment of the B49/B49Mod1 peptide series for the interruption of cancer cell adhesion may provide insight into the regulation of BST-2 and its interaction with cancer cells." (PMID 32155736, 2020). "Therefore, B49 and its analogs offer a promising anti-adhesion and therapeutic lead for BST-2-dependent cancers." (PMID 29523843, 2018). "Given the BST-2-independent effect of B49Mod1 in blocking immune cell to cancer adhesion, we developed a system to evaluate the effect of B49Mod1 on other adhesion molecules that may mediate cell: matrix interactions in the absence of BST-2." (PMID 29523843, 2018). "Bone marrow stromal antigen 2 (BST-2) mediates various facets of cancer progression and metastasis." (PMID 30514852, 2018). "The intracellular pathways controlled by the BST-2 cytoplasmic tail in the context of cancer cell migration and invasion are unknown." (PMID 29299143, 2017). "This BST-2-directed cell reprograming allows cancer cells to survive in circulation." (PMID 28300825, 2017). "The magnitude of BST-2 upregulation may depend on the basal level of cancer cell BST-2 because BST-2 level and the magnitude of fibroblast-mediated BST-2 upregulation are lower in Cal51 compared with MDA-MB-231." (PMID 28300825, 2017). "However, we have previously shown that BST-2 is activated via cancer cell to cancer cell interactions, resulting in phosphorylation of the double tyrosine motif on the BST-2 cytoplasmic tail." (PMID 29299143, 2017). "Therefore, future studies should identify the BST-2-directed cancer cell program that regulates stromal network structure and promotes individualized and collective cancer cell invasion." (PMID 29299143, 2017). "Recently, we demonstrated that it is the variant and not the level of BST-2 in cancer cells that regulates cancer cell clustering, which in turn promotes anoikis resistance." (PMID 29299143, 2017). "Our study identifies BST-2 dimerization as critical in the promotion of cancer cell adhesion." (PMID 28300825, 2017). "Whether BST-2 expressing cancer cells use membrane-anchored proteinases to remodel the basement membrane and to migrate through cross-linked ECM substrates remains to be determined." (PMID 29299143, 2017). "Moreover, the levels of Bcl-XL protein positively correlated with BST2 in the cancer tissues of NPC patients." (PMID 28617432, 2017). "First, the BST-2 ECD cysteine residues mediate formation of BST-2 dimers in cancer cells." (PMID 28300825, 2017). "Given the broad functionality of BST-2 and its ability to regulate signals involved in cancer, we expect that the pro-motility and anti-motility factors may be part of the global cancer interactome." (PMID 29299143, 2017). "We show that BST-2 silencing in various cancer cell lines inhibits cell motility." (PMID 29299143, 2017).
cancer (continued). "Additionally, BST2 protein levels positively correlated with Bcl-XL levels and negatively correlated with IκBα levels in xenografts in nude mice and cancer tissues of NPC patients." (PMID 28617432, 2017). "Our retrospective clinical investigation demonstrated that high levels of BST2 in cancer tissues may serve as an independent poor prognostic factor for patients with locally advanced NPC treated with platinum-based chemoradiotherapy." (PMID 28617432, 2017). "Thus, it is possible that MMTV infection of mammary epithelial cells leads to accumulation of epigenetic aberrations that change BST‐2 levels and affect the activity of cancer‐promoting pathways." (PMID 27042298, 2016). "BST‐2 expression is inducible in immune and cancer cells by cytokines." (PMID 27042298, 2016). "The significance of elevated BST‐2 in various cancers is beginning to evolve." (PMID 27042298, 2016). "Another plausible mechanism by which BST‐2 may promote cancer development and progression is through activating NF‐κB‐mediated signal transduction pathways." (PMID 27042298, 2016). "The molecular mechanism by which BST‐2 promotes cancer remains to be determined." (PMID 27042298, 2016). "Despite the contradictory effects of BST‐2 in various cancers in vitro, Sayeed et." (PMID 27042298, 2016). "In recent years, several studies reported the connection between BST2 and cancer." (PMID 26494939, 2015). "Results reveal that levels of BST-2 expression in various cancer types differ." (PMID 25860442, 2015). "There is direct evidence for a role for BST-2 in two cancers." (PMID 25860442, 2015). "However, there are still few studies about BST2 expression in human cancers and its potential as a cancer biomarker." (PMID 26494939, 2015). "The observed difference in survival between 4T1 cells and E0771 cells models could be attributed to (i) the level of aggressiveness of the cells; with E0771 cells being more metastatic than 4T1 cells, and (ii) the level of BST-2 in the different cancer cells." (PMID 25499888, 2014). "Furthermore, we found that the cellular basis for the role of BST-2 in promoting tumorigenesis include BST-2-directed enhancement in cancer cell adhesion, anchorage-independency, migration, and invasion." (PMID 25499888, 2014). "Although overexpression of BST-2 tethers virions on the cell membrane and negatively regulates virus replication, it is likely that elevated BST-2 expression might positively influence cancer cell behavior." (PMID 25499888, 2014). "An enhancement in cancer cell invasion also resulted when BST-2 was overexpressed in MCF-7 cells." (PMID 25499888, 2014). "A pragmatic strategy used here for normalizing endogenous BST2 expression experimentally could be applied towards increasing the effectiveness of standard cancer therapeutics in patients." (PMID 23840623, 2013). "BST2 overexpression could serve to identify patients likely to relapse after pro apoptotic cancer therapies." (PMID 23840623, 2013). "In addition high levels of BST2 expression have been observed on many cancer cell lines which correlates with reports of high levels of CMV antigen in certain tumors." (PMID 22072961, 2011). "For Group A, interferon-responsive elements were found for most of the genes, but not the cancer/metastasis-associated genes (BST2 is an exception), consistent with previous studies that did not identify these genes as IFN-regulated." (PMID 17233903, 2007). "This unique tethering mechanism, which involves modulating cell membrane organization and vesicle release, suggests that BST2's functions could be co-opted in pathological contexts beyond viral infection, such as regulating cell–cell communication and invasion in cancer." (PMID 41281378, 2025). "In addition, BST2 also plays some roles in the progression of cancer." (PMID 37143676, 2023). "However, limited data are available on BST2 expression in human cancer." (PMID 32054102, 2020).
cancer (continued). "Importantly, the treatment of shBST-2 cells with B49Mod1 did not change the pattern of cell adhesion, indicating that B49Mod1 may mostly inhibit BST-2-mediated cancer cell adhesion." (PMID 32155736, 2020). "Thus, cancer cells expressing BST-2 dimers may serve as a target or docking sites for other cells and ECM proteins to bind to tumors." (PMID 28300825, 2017). "Differences in BST‐2 effect on cancer cells could be due to the cell types used." (PMID 27042298, 2016). "This strategy does not require over-expression of BST-2, which has the risk of causing cancer." (PMID 26935098, 2016). "Hence we investigated the ability of BST-2 to promote cancer cell invasion using a Matrigel model." (PMID 25499888, 2014). "The ligand of ILT7 has been identified as bone marrow stromal cell antigen 2 (BST2, also known as CD317) widely expressed in human tissues to varying degrees and reported in several human cancer cell lines, as well as in a wide range of tumors." (PMID 39020402, 2024). "The TIMER database was used to analyze the correlation between mRNA expression of APOE, BGN, BST2, and C1QB and infiltrating immune cells in cancer tissues." (PMID 39650066, 2024). "For instance, B2M, SLPI, BST2, GAPDH, S100A8, S100A9, and HMGB1, despite their beneficial roles in various infections, they contribute to cancer cell proliferation, invasiveness, reduced survival, and increased disease severity across different cancers." (PMID 38589404, 2024). "For example, the overexpression of bone marrow stromal antigen 2 (BST2), also known as ILT7 ligand or tetherin, has been described on the surface of various human cancer cells." (PMID 36232698, 2022). "With the use of MD simulations, a possible mechanism of action of B18L emerged showing that B18L binds BST-2 and a model POPC/POPS membrane (a mimic of cancer cell membrane)." (PMID 32872253, 2020). "However, the domain of BST-2 that controls cancer cell motility is unknown." (PMID 29299143, 2017). "Recently, BST-2 dimerization mediated by the ECD cysteine residues has been shown to enhance cell to cell and cell to ECM interaction, as well as in promoting cancer cell survival through the disruption of the anoikis machinery." (PMID 29299143, 2017). "Second, similar to the role of BST-2 in adhesion, the ability of BST-2 to promote survival and growth of cancer cells in suspension is controlled by BST-2 dimerization." (PMID 28300825, 2017). "MM is characterized by elevated BST‐2 (HM1.24) expression in malignant plasma cells and in MM cancer stem cells (CSC)." (PMID 27042298, 2016). "These experiments demonstrate that BST-2 expression is crucial for cancer cell invasion and that suppressing BST-2 expression in cancer cells reduced the ability of the cells to invade the basement membrane." (PMID 25499888, 2014). "Cancer cells suppressed of BST-2 (sh137 and sh413) lost their ability to migrate to the scratched wounds compared with those expressing BST-2 (shControl) at both 6 h and 24 h time points." (PMID 25499888, 2014). "It has been shown that the innate immunity gene called bone marrow stromal antigen 2 (BST-2), also known as tetherin, CD317, and HM1.24 is overexpressed in several cancers." (PMID 25499888, 2014). "Of these genes, we selected TSPAN8, BST2, BMP7, and Col6A1 for further analysis, because these genes have been reported to be involved in tumorigenicity or cancer cell invasion and migration." (PMID 25221999, 2014). "The crosslinking of ILT7 and BST2 strongly inhibits the production of IFN-α and proinflammatory cytokines (e.g. TNF-α) by pDCs; however, the role of this interaction in cancer is still unclear." (PMID 39020402, 2024). "As a result, MUC1-C was also necessary for expression of (i) OAS1, which attenuates PAR synthesis during DNA repair and promotes the ability of cancer cells to survive replicative stress, and (ii) IFIT1-3, MX1 and BST2, among others, which confer DNA damage resistance." (PMID 35681561, 2022).
cancer (continued). "Among them, BST2, CALR, DDIT3, HSPA5, and TRIB3 were significantly up-regulated in cancer tissues." (PMID 34580365, 2021). "The last cysteine residue at position 91 is indispensable for BST-2-mediated promotion of cancer cell adhesion, and B49Mod1 (which contains three cysteine residues) may target the cysteine residues in the ECD of BST-2." (PMID 32155736, 2020). "We demonstrate that a key effect of BST-2 expression in cancer cells is the induction of enhanced non-proteolytic and proteolytic cell motility independent of cell proliferation, as well as the ability to overcome anoikis." (PMID 30514852, 2018). "Additional experiments show that suppression of BST-2 renders non-adherent cancer cells non-viable by sensitizing cells to anoikis." (PMID 30514852, 2018). "OE-BST-2D but not OE-BST-2M efficiently rescues colony formation in shBST-2 cells, indicating that BST-2 dimerization is required for growth of cancer cells independent of anchor." (PMID 28300825, 2017). "The ability of BST‐2‐expressing cancer cells to grow and form colonies independent of anchor positively correlates with anoikis resistance." (PMID 27042298, 2016). "Although BST2 has been identified to be overexpressed in a variety of cell lines from different cancer types, to our knowledge, there were no studies reporting BST2 protein expression in CRC tissue specimens." (PMID 26494939, 2015). "Normal mammary epithelial cells did not express high BST-2, however, cancer cell lines exhibited high levels of BST-2 mRNA and protein, consistent with a previous report, and suggestive of a potential role in mammary oncogenesis." (PMID 25499888, 2014). "Interestingly, the protein BST-2 (also called tetherin, CD317 and HM1.24) is elevated in various tumors and cancer cells with no subtype specificity, at least in breast cancer." (PMID 29523843, 2018). "Bone marrow stromal antigen 2 (BST-2) is one such gene whose role in cancer is not clear." (PMID 25499888, 2014). "Whether or not the amount of BST-2 expressed in a cell regulates interaction with B18L and the resultant cytotoxic effect on cancer cells remains to be determined, although MCF7-G11-TR5 have higher BST-2 and are more susceptible to B18L compared to parental MCF7 cells." (PMID 32872253, 2020). "However, in two-dimensional culture, we found that 4T1 cells but not E0771 cells with suppressed BST-2 expression have higher viability as measured by MTT assay, indicating that cell viability may not be implicated in the role of BST-2 in cancer cell behavior." (PMID 25499888, 2014). "In contrast, grade 3 cancer cell lines are unresponsive to TGF‐β signaling and BST‐2 expression is not inhibited." (PMID 27042298, 2016).
neurodegenerative disease (2 papers, 2022 to 2025). A disorder of the central nervous system characterized by gradual and progressive loss of neural tissue and neurologic function. "Interestingly, we found a greater number of BST2, HLA-E, PD-L1, and PDPN positive GFAP+ astrocytes in AD post-mortem brains compared to brains from non-symptomatic individuals, warranting further investigations on the roles that these markers play in neurodegenerative disease." (PMID 35592112, 2022).
neurologic disorders (2 papers, 2016 to 2021). "In conclusion, based upon the results of our comprehensive analysis of HHV-6A infected HA1800 cells, we revealed several genes correlated with neurologic disorders, especially CTSS, PTX3, CHI3L1, Mx1, CXCL16, BIRC3, and BST2 genes." (PMID 27344170, 2016).
bacterial infections (1 paper, 2015). "Although the role of BST2 in bacterial infections is unclear, BST2 gene product has been reported as an antiviral factor whose expression inhibits virus release from infected cells." (PMID 26566142, 2015).
digestive diseases (1 paper, 2025). "Notably, leptin (LEP), GDF15, and ADM showed the strongest associations with lung function, while BST2, THBS2, and CEACAM1 exhibited the most significant associations with digestive diseases." (PMID 40048323, 2025).
BST2 also shares sentences with these, for which no sentence is quoted: multiple myeloma (7 papers); prostate carcinoma (3); thyroid cancer (3); Alzheimer disease (2); bone metastasis (2); chromophobe carcinoma (2); gastric tumor (2); infectious disease (2); kidney cancer (2); lung squamous cell carcinoma (2); non-small cell lung carcinoma (2); ZIKV infection (2); acute myeloid leukemia (1); adenocarcinoma (1); Arthritis (1); B-cell acute lymphoblastic leukemia (1); breast (1); Burkitt lymphoma (1); chronic asthma (1); experimental autoimmune encephalomyelitis (1); H1N1 virus infection (1); heart failure (1); hematological malignancies (1); herpesvirus infections (1); Hypoalbuminemia (1); inflammatory bowel disease (1); invasive ductal carcinoma (1); leukemia (1); liver cancer (1); lupus erythematosus (1).
A further 17 diseases each share a sentence with BST2 in 1 paper.